MLKL (mixed lineage kinase domain like pseudokinase)
Diseases named in the same sentence as MLKL in open-access papers (continued):
Sharing a sentence is not in itself a finding about the gene and the disease.
Alzheimer disease (9 papers, 2020 to 2025). A progressive, neurodegenerative disease characterized by loss of function and death of nerve cells in several areas of the brain leading to loss of cognitive function such as memory and language. "Further to their role in the immune system, MLKL activity and necroptosis have also been implicated in the pathogenesis of a range of other clinical conditions, including neurodegenerative diseases such as amyotrophic lateral sclerosis, Alzheimer’s disease, and multiple sclerosis." (PMID 32358523, 2020). "The keywords include "necroptosis", "RIPK1", "RIPK3", "MLKL", "pMLKL", "necroptosis inhibitors", "Alzheimer’s disease", and "neurodegeneration"." (PMID 41042431, 2025). "Supporting its role in the diseases of the nervous system, both MLKL and phosphorylated MLKL levels were found to be elevated in derived postmortem tissues of patients with Parkinson’s disease and samples from the brains of patients with Alzheimer’s disease." (PMID 37373257, 2023). "Necroptosis, which is mediated by receptor-interacting protein kinase 1 (RIPK1 or RIP1), RIPK3 (or RIP3), and the pseudokinase MLKL, promotes necrotic cell death and neuroinflammation in Alzheimer’s disease (AD), amyotrophic lateral sclerosis (ALS), multiple sclerosis (MS), and PD." (PMID 38041169, 2023). "Increased necroptosis has been reported in the postmortem brains of Alzheimer’s disease patients, i.e., an increase in the expression of RIPK1, RIPK3, MLKL, and P-MLKL." (PMID 34515928, 2021).
inflammatory bowel disease (9 papers, 2017 to 2024). A spectrum of small and large bowel inflammatory diseases of unknown etiology. "For example, high levels of MLKL and RIP3 are associated with inflammatory bowel disease in children." (PMID 29527209, 2018). "The cell necroptosis executor protein MLKL (Mixed-lineage kinase domain-like) is involved in various diseases, including inflammatory bowel disease and neurodegenerative diseases; however, its precise role in PD remains unclear." (PMID 38041169, 2023). "Indeed, in both cultures, we observed a sharp increase in Mixed Lineage Kinase Domain Like Pseudokinase (MLKL) mRNA levels, which is known to be associated with Caspase 8 deficiency and Inflammatory Bowel Disease commonly observed in patients." (PMID 34608167, 2021). "Furthermore, the accumulation of phosphorylated MLKL at intercellular junctions accelerates necroptosis between neighbouring cells, which may be relevant to inflammatory bowel disease and other necroptosis-mediated enteropathies." (PMID 32561730, 2020). "Furthermore, we present robust protocols for detecting human Caspase-8, RIPK1, RIPK3, and MLKL and illustrate their utility for detecting dysregulated necroptosis in biopsies from patients with inflammatory bowel disease (IBD)." (PMID 38750308, 2024). "Pediatric patients with inflammatory bowel disease have elevated levels of RIP3 and MLKL in the inflammatory tissue, demonstrating a strong correlation between necroptosis and inflammatory disease." (PMID 38840220, 2024).
Obesity (9 papers, 2016 to 2025). Accumulation of substantial excess body fat. "The last piece of evidence suggesting that necroptosis is implicated in the inflammatory consequences of obesity comes from studies using mice deficient for MLKL." (PMID 36175539, 2023). "As RIPK3 can regulate the death- and inflammation-inducing activity of both caspase-8 and MLKL in disease-causing macrophages, direct comparisons of mutant animals in the same obesity and MAFLD model are required to define their pathological roles and divergent activities." (PMID 39532538, 2025). "Collectively, these findings highlight MLKL as an attractive therapeutic target to combat the growing obesity pandemic and metabolic disease." (PMID 39532538, 2025). "This study shows how necroptotic effector MLKL can induce obesity and perturb lipid metabolism to drive MAFLD progression, independent of RIPK3 that regulates inflammatory events." (PMID 39532538, 2025). "In our hands, MLKL acts independently of canonical RIPK3 signaling to drive obesity and metabolic dysfunction." (PMID 39532538, 2025). "Here, we directly contrast the contribution of RIPK3, along with caspase-8 in myeloid cells, and MLKL signaling in obesity and MAFLD development." (PMID 39532538, 2025). "In comparison, MLKL appears to drive obesity with aging to promote MAFLD development in a manner independent of canonical RIPK3 signaling." (PMID 39532538, 2025). "Overall, the research sheds light on the intricate interplay between MLKL, lipid metabolism, and metabolic health, offering valuable insights for understanding and potentially targeting MLKL in the context of obesity-related disorders." (PMID 38474061, 2024). "The primary goal of this study is to investigate the role of MLKL, the key effector molecule in the necroptosis pathway, in obesity-driven MASH." (PMID 38474061, 2024). "Unfortunately, there is little focus on the inflammatory or cell death features in WAT and hence the understanding of the role of MLKL in obesity-induced inflammation requires further investigation." (PMID 36175539, 2023). "Inhibition of MLKL prevented obesity-induced insulin resistance in mice and promoted intracellular Listeria replication." (PMID 36828808, 2023). "However, upon HFD feeding, Mlkl−/− mice exhibited lower serum insulin, ALT, and cholesterol levels, compared with HFD-fed WT controls, supporting the idea that MLKL drives obesity-induced metabolic dysfunction." (PMID 39532538, 2025). "Based on the differing obesity and inflammatory phenotypes observed in RIPK3- versus MLKL-deficient mice, we questioned whether MLKL requires RIPK3 activity to alter lipid metabolism in the liver of HFD-fed mice." (PMID 39532538, 2025). "Although the role of upstream kinases RIPK1 and RIPK3 in obesity and MAFLD remain debatable, there are numerous reports that MLKL deficiency protects mice from MAFLD." (PMID 39532538, 2025). "We next examined the effect of the RIPK3 substrate MLKL on the development of obesity and MAFLD." (PMID 39532538, 2025). "How MLKL deficiency protects mice from obesity is unclear, but one recent study proposed that MLKL, and not RIPK3, drives white adipose tissue differentiation." (PMID 39532538, 2025). "Ultimately, our study also offers a new avenue and perspective on how targeting divergent MLKL functions, beyond cell death, may limit obesity and MAFLD." (PMID 39532538, 2025). "Thus, increased fat utilization by thermogenic adipocytes in the absence or reduction of MLKL contributes to the resistance to diet-induced obesity observed in these mouse models." (PMID 38474061, 2024). "In patients with MASLD and obesity, MLKL is also highly expressed and phosphorylated in multiple organs including liver and adipose tissue as well as multiple cell types, including liver parenchymal and non-parenchymal cells, such as hepatic stellate cells and immune cells." (PMID 38195700, 2024).
Obesity (continued). "MLKL, which can directly induce necroptosis, has been reported to be involved in different inflammatory diseases, including tumor necrosis factor-induced shock, ischemia–reperfusion injuries, and obesity." (PMID 37924005, 2023). "Additionally, MLKL was found to be involved in the development of obesity-induced insulin sensitivity in liver, but had only a minor effect on hepatic inflammation." (PMID 33616081, 2021). "Thus, the mechanisms governing the interplay between obesity/high-fat diet and MLKL induction may vary depending on the cell type and specific stimulus." (PMID 38195700, 2024). "Considering that obesity/MASLD is a systemic disease, it would also be intriguing to assess how MLKL functions in other organs, such as the gut and adipose tissue." (PMID 38195700, 2024). "To evaluate whether hematopoietic MLKL expression contributes to obesity, we examined C57BL/6 mice reconstituted with WT control or Mlkl−/− bone marrow in our dietary model." (PMID 39532538, 2025). "Our study reveals that caspase-8 induces damaging inflammation to saturated fatty acids, whereas MLKL uniquely regulates obesity and MAFLD via noncanonical actions on lipid metabolism." (PMID 39532538, 2025). "More importantly, we delineate a noncanonical, RIPK3-independent role for MLKL in lipid metabolism and the development of obesity and MAFLD." (PMID 39532538, 2025). "Yet, the contradictory reports on the role of MLKL during obesity do not facilitate our understanding of this cell death modality in the modulation of metabolic disorders." (PMID 40961178, 2025). "Similarly, elevated RIP3 expression has been found in the visceral adipose tissue of individuals with obesity and type 2 diabetes, showing a positive correlation between RIP3 expression, MLKL, and metabolic serum markers." (PMID 38195700, 2024). "Therefore, MLKL drives obesity and MAFLD in aged and HFD-fed mice but does not contribute substantially to inflammation." (PMID 39532538, 2025). "Instead, our data suggest that MLKL may have noncanonical activities in obesity and MAFLD." (PMID 39532538, 2025). "The fact that adipose tissue inflammation is not affected by an HFHFrHC diet or MLKL supports a non-necroptotic function of MLKL in regulating lipid metabolism in adipose tissue, which warrants further investigation for potential therapeutic targets in obesity-related conditions." (PMID 38474061, 2024). "In contrast, MLKL, divergent to RIPK3, contributes to both obesity and MAFLD in a manner largely independent of inflammation." (PMID 39532538, 2025). "Importantly, studies have highlighted the pivotal role of MLKL-mediated non-canonical functions in the pathogenesis of MASLD and obesity." (PMID 38195700, 2024).
prostate carcinoma (9 papers, 2020 to 2024). A carcinoma that arises from epithelial cells of the prostate gland. "In conclusion, IDOAMP directly inhibited Aurora kinase A and promoted the RIPK1/RIPK3/MLKL necrosome activation to inhibit the prostate cancer." (PMID 35965682, 2022). "For example, RIPK3 inhibits prostate cancer progression by activating MLKL through phosphorylation and necroptosis activation." (PMID 34869390, 2021). "When prostate cancer cells were treated with the MLKL inhibitor NSA, the inhibition of proliferation induced by overexpression of RIP3 stopped, indicating that necroptosis is the main cause of tumor proliferation inhibition." (PMID 32984054, 2020). "In the Atg5-deficient prostate cancer cell line DU-145, sorafenib could mediate necroptosis by inducing the RIPK1/RIPK3/MLKL pathway, and this process can be blocked by the RIPK1 inhibitor Nec-1." (PMID 34869390, 2021). "Furthermore, our results also showed that RIP3 can inhibit the proliferation and tumorigenicity of prostate cancer cells both in vitro and in vivo by phosphorylating MLKL, which were reversed by MLKL inhibitor treatment, indicating that necroptosis was involved in cell death." (PMID 32984054, 2020).
renal fibrosis (9 papers, 2018 to 2025). A final common manifestation of a wide variety of chronic kidney diseases characterized by glomerulosclerosis and tubulointerstitial fibrosis. "Collectively, these data indicated that both RIPK3 and MLKL contributed to progression of renal fibrosis post IRI." (PMID 30158627, 2018). "Furthermore, we found that treatment with RIPK1 inhibitor, Nec-1 significantly inhibited the activation of the RIPK1/RIPK3/MLKL signaling pathway, ameliorated renal dysfunction, and reduced kidney inflammation and renal fibrosis." (PMID 36756299, 2023). "Here we found that deletion of RIPK3 or MLKL alleviated the NLRP3 inflammasome activation and IL-1β release in kidney after IRI corresponding with the reduction of renal fibrosis." (PMID 30158627, 2018).
cervical carcinoma (8 papers, 2021 to 2025). A carcinoma arising from either the exocervical squamous epithelium or the endocervical glandular epithelium. "A high level of MLKL in peripheral blood mononuclear cells from cervical cancer patients was associated with improved overall survival." (PMID 38576612, 2024). "Lastly, the downregulation of MLKL transcript has been linked with poor prognosis in breast, colorectal, and cervical cancers." (PMID 37373257, 2023). "In contrast, some studies associate a low level of MLKL expression with a reduction in the overall survival of numerous cancer-resected patients, including those suffering from pancreatic adenocarcinoma, cervical cancer, and breast cancer." (PMID 37373257, 2023). "Our results confirmed that AL promoted upregulation of RIPK3 expression in cervical cancer HeLa cells and enhanced phosphorylation level of MLKL, which was reversed in the presence of bafilomycin A1 (BafA1)." (PMID 33927214, 2021). "Notably, when the U937 macrophages were cocultured with cervical cancer cells, the decreased expression and phosphorylation of MLKL were observed along with reduced necroptosis." (PMID 38576612, 2024). "Additionally, blocking MLKL expression might regulate macrophage polarization, offering a novel therapeutic strategy for cervical cancer." (PMID 40264780, 2025). "Plasma MLKL and HPV DNA are readily measurable in clinical labs, suggesting their combined detection in cervical cancer diagnosis and disease monitoring." (PMID 40264780, 2025). "Increasing the radiosensitivity of cervical cancer by inducing necroptosis via ROS generation and increased expression of RIP and MLKL." (PMID 38239395, 2023). "Necrosis of cervical cancer cells through phosphorylation of RIPK1, RIPK3, and MLKL, thereby triggering an antitumor immune response in cervical cancer." (PMID 36349142, 2022).
chronic kidney disease (8 papers, 2021 to 2026). Impairment of the renal function secondary to chronic kidney damage persisting for three or more months. "Finally, combination therapy with inhibitors of MLKL and apoptosis may provide additive protection, with the ultimate aim of preventing acute and chronic kidney disease following kidney IR." (PMID 38022500, 2023). "From AKI to chronic kidney disease (CKD), under the regulation of IRI, the expression and interaction of RIPK3 and MLKL can induce necrosis of proximal renal tubular cells and promote the activity of inflammasome." (PMID 34977874, 2021).
dermatitis (8 papers, 2018 to 2025). An inflammatory process affecting the skin. "Caspase-8 ablation combined with mutation of the MLKL phosphorylation sites completely prevented skin lesion development in ZBP1caE-het mice, demonstrating that ZBP1ca induces skin inflammation by triggering necroptosis and caspase-8-mediated apoptosis." (PMID 38849574, 2024). "Our study supports this paradigm, as in addition to preventing RIPK1 deficiency-caused spontaneous skin inflammation, keratinocyte-specific MLKL deficiency also prevented exogenous disturbance-induced skin inflammation." (PMID 36344541, 2022). "The significance of cell death in driving dermatitis is further supported by the fact that loss of caspase-8 and either MLKL or RIP3 is protective in these mice." (PMID 32671059, 2020). "ΔKerOTULIN mice only deficient for MLKL in keratinocytes were partially protected from dermatitis." (PMID 34625556, 2021). "To address whether MLKL-dependent necroptosis drives skin inflammation also in Casp8E-KO mice, we crossed them to MlklAA/AA mice, which express a mutated version of MLKL that cannot be phosphorylated by RIPK3 due to substitution of serines at positions 345 and 347 to alanines." (PMID 38849574, 2024). "There was a very minor increase in the levels of pMLKL-S345 detected in localised areas of the skin of Shpnm/m compared to Shpn+/m mice, suggesting that MLKL-induced necroptosis contributes marginally to the dermatitis observed in the Shpnm/m animals." (PMID 38783091, 2024). "This is suggesting that RIPK3-mediated inflammation contributes to dermatitis independently of MLKL activation and that apoptotic cell death is the main driver of dermatitis." (PMID 38783091, 2024). "Our study provides the novel evidence that MLKL-mediated keratinocyte necroptosis is a promising pharmaceutic target for dermatitis of CHS." (PMID 36344541, 2022). "The observation that genetic deletion of both FADD and MLKL in keratinocytes protects ΔKerOTULIN mice from dermatitis development, proved that cell death of keratinocytes is the driving force of the cutaneous inflammation developing in ΔKerOTULIN mice." (PMID 34625556, 2021). "Therefore, inhibition of RHIM-dependent RIPK1 signaling prevented MLKL-independent skin inflammation induced by ZBP1ca expression in keratinocytes." (PMID 38849574, 2024). "Moreover, transgenic expression of C-terminally truncated constitutively active ZBP1 (ZBP1ca) in mouse epidermis caused skin inflammation that was only partially inhibited by abrogation of RIPK3-MLKL-dependent necroptosis and fully prevented by combined deficiency in MLKL and caspase-8." (PMID 38849574, 2024). "MLKL deficiency could ameliorate but not prevent dermatitis development in ΔKerOTULIN mice, suggesting that both FADD-dependent apoptosis and MLKL-dependent necroptosis are driving the skin lesion development in ΔKerOTULIN mice." (PMID 34625556, 2021). "Specifically, TNF-induced apoptosis is responsible for skin inflammation since Casp8 heterozygosity can significantly ameliorate the dermatitis, while multi-organ inflammation is predominantly driven by RIPK3/MLKL-induced necroptosis." (PMID 38783091, 2024). "These mice are known to succumb to aberrant skin inflammation induced by RIPK3 and MLKL-mediated necroptosis." (PMID 38783091, 2024). "The complete rescue from dermatitis upon genetic deletion of both FADD and MLKL proves that keratinocyte cell death is the driving force of the skin inflammation and tumorigenesis in ΔKerOTULIN mice." (PMID 34625556, 2021). "The deletion of MLKL did not prevent the onset of skin inflammation in the TARF2E-KO mice." (PMID 40006996, 2025). "Interestingly, while co-deletion of Sharpin and RIPK3 delays the onset of the dermatitis, MLKL co-deletion does not affect the skin inflammation observed in the Shpnm/m." (PMID 38783091, 2024). "Interestingly, while RIP3 loss delays the development of dermatitis in SHARPIN deficient mice, MLKL loss does not affect the development of dermatitis." (PMID 32671059, 2020).
dermatitis (continued). "Collectively, these results demonstrate that caspase-8-mediated apoptosis is responsible for the lethal dermatitis in mice lacking HOIP or HOIL-1 in keratinocytes and that RIPK3/MLKL-mediated necroptosis does not contribute to the disease." (PMID 30254289, 2018).